FANCD2 (FA complementation group D2)
Diseases named in the same sentence as FANCD2 in open-access papers (continued):
Sharing a sentence is not in itself a finding about the gene and the disease.
infection (9 papers, 2013 to 2026). The state of being infected such as from the introduction of a foreign agent such as serum, vaccine, antigenic substance or organism. "Only 25% of the novel junctions arising from depletion of USP1–PCNA/FANCD2/FANCI overlap with ∆UL138STOP infections, suggesting an important role for UL138 in directing these pathways." (PMID 41533576, 2026). "By contrast, in ∆UL138STOP infection, SNV counts increased in the USP1–PCNA/FANCD2/FANCI knockdown relative to any other knockdown in ∆UL138STOP infection." (PMID 41533576, 2026). "The combined depletion of USP1–PCNA/FANCD2/FANCI in WT infection triggered a robust increase in inversions and deletions across the entire CMV genome (lightest blue bars) relative to the siNTC." (PMID 41533576, 2026). "Further, depletion of USP1–PCNA/FANCD2/FANCI was sufficient to compromise viral genome integrity in WT infection." (PMID 41533576, 2026). "UL138-UAF1–USP1 stimulates deubiquitination of PCNA and FANCD2 during infection with restrictive effects on viral genome synthesis." (PMID 41533576, 2026). "PCNA and FANCD2 were also relocalized to RCs in ∆UL138STOP infection, which suggests this phenomenon occurs independently of UL138, as was observed for USP1." (PMID 41533576, 2026). "These FA-like cells were generated by infection of CD34+ cord blood cells with a lentivirus expressing a shRNA against FANCD2." (PMID 36441774, 2022). "The percentage of cells harboring p-H2AX and FANCD2 foci increased markedly between 4 and 20 h after infection with DH10B pBACpks or treatment with MMC." (PMID 29559578, 2018). "To gain more insight into the role of UL138 and USP1–PCNA/FANCD2/FANCI in controlling DDR pathways and maintaining CMV genome integrity, we analyzed the distribution and type (e.g. inversions, deletions, or duplications) of structural variants in each of our infection and knockdown conditions." (PMID 41533576, 2026). "By contrast, the rearrangements in the UL region arising in UL138-mutant infection occurred independently of repeat sequences and USP1–PCNA/FANCD2/FANCI." (PMID 41533576, 2026). "Compared to the NTC, USP1 depletion in WT infection led to a modest, but significant, increase in mUb–PCNA and mUb–FANCD2 at 48 hpi and 72 hpi, respectively, resembling the phenotype observed in ∆UL138STOP infection." (PMID 41533576, 2026). "Compared to NTC, depletion of PCNA/FANCD2/FANCI or PCNA/FANCD2/FANCI combined with USP1 increased viral genome synthesis in WT and ∆UL138STOP infections." (PMID 41533576, 2026). "It has been demonstrated that efficient productive infection requires RAD51 and, to a lesser extent, FANCD2, suggesting that homologous recombination is important for high-level extrachromosomal replication." (PMID 24260277, 2013). "BRCA1, BRCA2, FANCI, and FANCD2 were substantially downregulated following WT-H. pylori infection, but not upon infection with the ΔcagA H. pylori strain, highlighting the CagA-dependence in their downregulation." (PMID 35163588, 2022). "Finally, we were intrigued by finding that depletion of USP1–PCNA/FANCD2/FANCI did not increase junctions beyond the disruption of UL138 in infection." (PMID 41533576, 2026). "FANCD2-depleted cells formed significantly fewer colonies than HeLa cells transfected with a scrambled siRNA 7 days after infection with DH10B pBACpks but not after infection with DH10B pBAC vector." (PMID 29559578, 2018). "USP1 depletion in ∆UL138STOP infection increased mUb–PCNA, but did not have a statistically significant effect on mUb–FANCD2 compared to the NTC control." (PMID 41533576, 2026). "In the same way as was seen with p-H2AX/FANCD2 foci, 53BP1 and RPA colocalized in subnuclear foci in a time-dependent manner in MMC-treated or pks+E. coli-infected cells but not after infection with E. coli hosting the pBAC vector." (PMID 29559578, 2018).
adenocarcinoma (6 papers, 2014 to 2024). A common cancer characterized by the presence of malignant glandular cells. "Thus, in the future, it would be of interest to further investigate the relationship between the newly confirmed sex cord precursor and an adenocarcinoma phenotype known to develop in the Fancd2−/− model." (PMID 37174061, 2023). "In line, CDDP-resistant H460, H1975 and mouse adenocarcinoma cells all displayed strongly elevated mTOR signaling, characterized by phosphorylation of mTORC1 target sites (p70S6KT389, 4E-BP1T37/46, and ULK1S757) and increased expression of FancD2." (PMID 32943635, 2020). "The frequencies may suggest that adenocarcinomas tumors have higher percentage of FANCD2 foci negative tumors as comparing to squamous cell carcinoma tumors." (PMID 25566506, 2014).
head and neck tumors (1 paper, 2013). "On the fancD2-sufficient background, K14E6E7/FancD2+/+ mice developed an increased number of overt head and neck tumors compared to K14E7/FancD2+/+ mice, consistent with our prior studies demonstrating an ability of E6 to augment the efficiency of E7-driven head and neck tumorigenesis." (PMID 24086435, 2013). "Thus, fancD2 deficiency did not lead to an increased susceptibility of E6 transgenic mice to head and neck tumors." (PMID 24086435, 2013). "On fancD2-sufficient background, only two of 26 K14E6/FancD2+/+ mice (8%) developed overt head and neck tumors, which was not significantly different from that observed in nontransgenic (NTG) mice." (PMID 24086435, 2013).
hematologic malignancies (1 paper, 2025). "Notably, we show that the combined loss of Lnk and Fancd2 does not reduce survival or increase hematologic malignancies of mice with single Lnk knockout during aging." (PMID 41165757, 2025).
kidney disease (1 paper, 2024). "Collectively, these findings highlight the potential of targeting DNA damage pathways, such as via restoring expression of repair factors like KAT5, ATR, FANCD2 and ERCC1 in kidney cells, as a therapeutic approach to slow down the progression of kidney disease in both tubular cells and podocytes." (PMID 38773208, 2024).
FANCD2 also shares sentences with these, for which no sentence is quoted: Fanconi anemia complementation group D2 (9 papers); genetic disease (4); head and neck squamous cell carcinoma (3); colon adenocarcinoma (2); triple-negative breast carcinoma (2); acute myeloid leukemia (1); Allergy (1); Burkitt lymphoma (1); carcinoid tumor (1); cardiovascular diseases (1); Charcot-Marie-Tooth disease (1); childhood cancer (1); chromosomal instability syndrome (1); Cockayne syndrome (1); cutaneous melanoma (1); cystadenoma (1); DOCK8 immunodeficiency syndrome (1); ductal carcinomas (1); ependymoma (1); epithelial ovarian tumor (1); familial Alzheimer disease (1); familial breast cancer (1); focal segmental glomerulosclerosis (1); gallbladder cancer (1); Glutamate formiminotransferase deficiency (1); granulosa cell tumour (1); gynecological cancers (1); histiocytic sarcoma (1); hyperglycerolemia (1); immunodeficiency (1).
A further 38 diseases each share a sentence with FANCD2 in 1 paper.